ADAMTS1 (ADAM metallopeptidase with thrombospondin type 1 motif 1)
Diseases named in the same sentence as ADAMTS1 in open-access papers (continued):
Sharing a sentence is not in itself a finding about the gene and the disease.
Down syndrome (5 papers, 2018 to 2024). "ADAMTS-1 is expressed in mouse and rat brains during development; in motor neurons in injured mice; and in the frontal cortex of humans with Down’s syndrome, Alzheimer’s disease, and Pick’s disease." (PMID 32150898, 2020). "Several genes associated previously with heart anomalies in Down syndrome, SH3BGR, DCSR6 and ADAMTS1, were co-injected (30pg each)." (PMID 29760202, 2018). "In an earlier study, we showed that Adamts1 deficiency causes an aortic syndromic disease similar to that found in MFS mice, identified Adamts1 as an important mediator of vascular homeostasis, and demonstrated depressed levels of aortic ADAMTS1 protein in MFS mice and patients." (PMID 38177536, 2024). "Previous studies have shown that ADAMTS1, within 665 kb of APP on chromosome 21, has elevated expression in Down’s syndrome and LOAD brain and is a potential neuroprotective gene or neuroinflammatory gene important to microglial response." (PMID 33419465, 2021). "Notably, three genes outside of the deletions (JAM2, ADAMTS1, and ETS2) and within the Down syndrome critical region (DSCR) were downregulated in RD_P26 NESCs when compared to euploid NESCs." (PMID 35186010, 2021).
glioma (5 papers, 2007 to 2021). A benign or malignant brain and spinal cord tumor that arises from glial cells (astrocytes, oligodendrocytes, ependymal cells). "Our in silico studies showed a positive correlation of ADAMTS1 with endothelial markers in glioma, association that we further corroborated performing in vitro co-culture assays of GBM and endothelial cells." (PMID 33396280, 2020). "Increased levels of ADAMTS1 lead to an increased cleaved IGFBP2, one of its target genes, which is associated with poor prognosis in gliomas." (PMID 34316702, 2021). "In this report we disclose an increased expression of ADAMTS1 according to grading of gliomas and it emerges as a bad prognosis marker for this neoplasia, mainly at its earlier stages." (PMID 33396280, 2020). "Here, an initial in silico analysis of glioma datasets with a relevant number of patients allowed us to observe a positive correlation of ADAMTS1 and endothelial markers with glioma progression." (PMID 33396280, 2020). "In line with the relevance of angiogenesis mechanisms during glioma progression and previous findings that remarked the actions of ADAMTS1 in endothelial and vasculature-related events, we looked at the correlation of ADAMTS1 with endothelial factors." (PMID 33396280, 2020). "Now, we focus our study in the specific contribution of the extracellular protease ADAMTS1 in glioma, first using in silico analyses of public available RNA-Seq datasets, and second performing a series of experimental approaches with glioblastoma cells." (PMID 33396280, 2020). "First of all, we observed a positive correlation between advanced glioma stages and an increasing ADAMTS1 gene expression in both datasets including a total of 1342 gliomas." (PMID 33396280, 2020). "According to these observations we analyzed the relevance of ADAMTS1 for the survival of glioma patients." (PMID 33396280, 2020). "Further evaluation of glioma samples, mostly focused in GBM, and of qualified databases, verified the presence of IGFBP2 proteolysis in gliomas and revealed a significant correlation between ADAMTS1 and IGFBP2." (PMID 24962328, 2014). "Looking back to the data of ADAMTS1 as bad prognosis factor at early stages of glioma evolution, we postulate the major contribution of this protease in stem-like cells during such period, also according to the specific characteristics of the TME in that earlier tumor phase." (PMID 33396280, 2020). "Furthermore, we already suggested ADAMTS1 plays a role in glioma through its action on IGFBP2 (insulin-like growth factor-binding protein 2) but without any functional outcomes involving the plasticity of GBM cells." (PMID 33396280, 2020). "We first performed an in silico study of ADAMTS1 and endothelial markers in human gliomas, providing the basis to further assess these molecules in several primary glioblastoma-initiating cells and established GBM cells with the ability to acquire an endothelial-like phenotype." (PMID 33396280, 2020). "Using gene expression public databases, we confirmed that IGFBP2 is a poor prognosis marker for gliomas, and we also observed an important contribution of ADAMTS1.Finally, we showed the impact of ADAMTS1 on IGFII-mediated IGF1R phosphorylation and cellular migration." (PMID 24962328, 2014). "We also sought to determine by immunohistochemistry whether glioblastoma multiforme (GBM) cases, the most aggressive type of glioma, express ADAMTS1 and produce both the intact and the cleaved forms of IGFBP2." (PMID 24962328, 2014). "Our results support a functional interaction between IGFBP2 and ADAMTS1 and suggest the need to evaluate post-translational modifications of IGFBP2 in glioma, in order to approach new therapies." (PMID 24962328, 2014). "However, it is not entirely clear if proteolytic degradation of versican by MMP-2 and ADAMTS-1 and 4 induced by TGF-β2 has a pathophysiological role in glioma progression." (PMID 17453002, 2007).
glioma (continued). "Furthermore, these analyses detected the cleaved form of IGFBP2, showing a statistically significant correlation between the levels of this processed form with that of ADAMTS1, which supports our hypothesis that ADAMTS1 cleaves IGFBP2 in glioma." (PMID 24962328, 2014). "Accordingly, the analysis of ADAMTS1 expression separating mutant and wild type (WT) IDH status confirmed significant higher levels of this protease in WT IDH gliomas, as the vast majority of superior grade IV gliomas do not present these mutant forms." (PMID 33396280, 2020).
heart failure (5 papers, 2014 to 2026). Inability of the heart to pump blood at an adequate rate to meet tissue metabolic requirements. "More importantly, in a pressure-loaded mouse model, specific knockout of Adamts1 in myofibroblasts significantly reduced myocardial fibrosis and restored cardiac function to normal levels—establishing a direct causal relationship for ADAMTS1′s pathogenic role in pressure-loaded heart failure." (PMID 41440846, 2025). "Based on these findings, targeting the ADAMTS1 pathway offers a significant therapeutic approach to delay the progression from myocardial injury to heart failure, demonstrating substantial potential for clinical translation." (PMID 41440846, 2025). "The role of aggrecanase activity exerted by ADAMTS1, -4, and -8 in heart failure progression will hopefully also be addressed in studies to come." (PMID 24595230, 2014). "Previously, adenoviral overexpression of glypican-6 in cultured cardiomyocytes was shown to increase protein synthesis and induce hypertrophy and heart failure signature genes, suggesting glypican-6 as a relevant ADAMTS1 and ADAMTS5 target in cardiac development." (PMID 38750698, 2024). "Furthermore, genes for fibrotic regulators, such as TGFβ1, TIMP1, TIMP3, TIMP4, and ADAMTS1, were linked to CLIC expression, reinforcing the hypothesis that CLICs contribute to fibrotic progression and ECM remodeling in human heart failure." (PMID 41521401, 2026). "This study revealed significantly elevated expression levels of both ADAMTS1 and ADAMTS4 in myocardial tissue, suggesting the potential role in the characteristic extracellular matrix dysregulation observed in heart failure." (PMID 41440846, 2025).
infertile (5 papers, 2013 to 2023). "It will be interesting to observe whether mice containing null mutations for ADAMTS-1, -5 and, -8 are infertile." (PMID 23947778, 2013). "(2000) also found ADAMTS1 null mice had a significantly low number of pups and delivery rate, it suggested ADAMTS1 null female mice were infertile." (PMID 32529744, 2020). "Nevertheless, an over expression of ADAMTS1 will lead to excessive cleavage of heparin, rapid liquefaction of semen thereby affecting spermatozoon survival and the overall fertilization process, and this may be directly related to infertility in ROS groups." (PMID 26321892, 2015). "A lack of ADAMTS-1 results in a decrease in female fertility and could influence human infertility." (PMID 26840413, 2016).
polycystic ovary syndrome (5 papers, 2017 to 2023). A disorder that manifests as multiple cysts on the ovaries. "The expression and functional activity of ADAMTS-1 in cumulus cells are closely related to the ability of the oocyte to fertilize, and a decrease in the expression of this metalloproteinase is associated with impaired maturation and quality of oocytes in women with polycystic ovary syndrome." (PMID 38068943, 2023). "According to previous studies, the expression level of ADAMTS1 in the granulosa cells of polycystic ovarian syndrome (PCOS) patients and the mechanism for regulating oocyte quality and embryonic development potential are still unclear." (PMID 33912563, 2021). "In recent years, several investigators have demonstrated a close correlation between ADAMTS1 levels in human CCs or follicle fluids and impaired oocyte quality in polycystic ovary syndrome (PCOS) patients." (PMID 31974739, 2020).
gastric tumors (4 papers, 2015 to 2024). "ADAMTS1 protein expression also negatively correlates with the vascular density of primary gastric tumors." (PMID 32456248, 2020). "The relative mRNA expression levels of ADAMTS1 were significantly lower in the methylated primary gastric tumor tissues, compared with the unmethylated primary gastric tumor tissuess." (PMID 25936341, 2015). "Together, these results suggested for the first time, to the best of our knowledge, ADAMTS1 as a novel antitumor protease, and this function was lost following epigenetic silencing in the gastric cancer cells and gastric tumor tissues." (PMID 25936341, 2015). "In the present study, the methylation status of the ADAMTS1 promoter was assessed in these primary gastric tumor tissues and in normal gastric tissues using MSP." (PMID 25936341, 2015). "The results revealed that the frequency of ADAMTS1 methylation in primary gastric tumor tissues was significantly higher, compared with the corresponding normal gastric tissues." (PMID 25936341, 2015). "The downregulation in the expression of ADAMTS1 was correlated with its promoter methylation in the primary gastric tumors and gastric cancer cell lines." (PMID 25936341, 2015). "Methylation of the ADAMTS1 gene was significant higher in primary gastric tumor tissues compared with normal gastric tissues (P=0.009)." (PMID 25936341, 2015). "It was previously observed that the mRNA and protein levels of ADAMTS1 are downregulated in primary gastric tumors." (PMID 25936341, 2015). "Methylation of the ADAMTS1 gene was detected in 27 (48%) primary gastric tumor tissues and eight (14%) corresponding normal gastric tissues." (PMID 25936341, 2015). "The present study demonstrated that the frequency of ADAMTS1 methylation in primary gastric tumors and gastric cancer cell lines was significantly higher than in normal gastric tissues and the normal gastric cell line." (PMID 25936341, 2015). "Our previous study reported low mRNA expression levels of ADAMTS1 in 56 primary gastric tumors." (PMID 25936341, 2015). "Furthermore, the frequency of ADAMTS1 methylation was significantly higher in primary gastric tumor tissues than in gastric cancer cell lines." (PMID 25936341, 2015). "In addition the relative mRNA levels of ADAMTS1 were significantly lower in the methylated primary gastric tumor tissues compared with those in the unmethylated primary gastric tumor tissues (P=0.043)." (PMID 25936341, 2015). "The aim of the present study was to examine whether the reduction in the expression of ADAMTS1 is due to aberrant methylation of the gene in primary gastric tumor tissues and gastric cancer cell lines." (PMID 25936341, 2015). "The present study investigated the mRNA expression of ADAMTS1 in five human gastric cancer cell lines and one immortalized normal gastric cell line, and analyzed the methylation status of ADAMTS1 using MSP in the cell lines and primary gastric tumor tissues." (PMID 25936341, 2015). "Whereas the ADAMTS1 gene expression level correlates with OS in stomach cancer patients, it is not an independent prognostic biomarker for GC, thus more validation studies are required." (PMID 33851708, 2021). "There are no previous studies describing the methylation status of ADAMTS1 in human gastric tumor tissues." (PMID 25936341, 2015).
glioblastoma (4 papers, 2010 to 2020). The most malignant astrocytic tumor (WHO grade IV). "In addition to U87-MG and U251-MG, we evaluated gene and protein expression of ADAMTS1 in two more recognized human glioblastoma cell lines (U373-MG and T98G)." (PMID 33396280, 2020). "In addition, high expression of ADAMTS1 correlates with higher levels of cleaved IGFBP2 in glioblastoma multiforme cases." (PMID 24962328, 2014). "ADAMTS1 negatively regulates tumor growth and metastasis, whereas TIMP2 takes part in degrading ECM (extracellular matrix) and regulating the invasion process, considered the root cause of the high recurrent incidence in glioblastoma." (PMID 21637621, 2010).
hepatocellular carcinoma (4 papers, 2011 to 2025). A malignant tumor that arises from hepatocytes. "In hepatoma cells, expression of ADAMTS1 is regulated differentially by SP1 (specificity protein 1) and USF1 (upstream stimulatory factor 1) under normoxic and hypoxic conditions." (PMID 29212212, 2017). "Similar to our study, ADAMTS1 was also poorly expressed in hepatocellular carcinoma (HCC) compared to normal liver tissues, but did play a critical role in indirectly promoting hepatic tumorigenesis through aggravating hepatic fibrogenesis, where it was produced in abundance." (PMID 38263290, 2024).
Hypertension (4 papers, 2018 to 2025). The presence of chronic increased pressure in the systemic arterial system. "Clinical studies showing the correlation between plasma SPARC levels and blood pressure and inflammatory markers in plasma indicate that elevation of SPARC and ADAMTS1 might be a possible predictive diagnostic marker for vascular injury in the setting of hypertension." (PMID 40362650, 2025).
Lewis lung carcinoma (4 papers, 2011 to 2025). "Overexpression of ADAMTS-1 promotes pulmonary metastasis of Lewis lung carcinoma cells and a proteinase-inactivated mutant of ADAMTS-1 inhibited their metastasis, indicating that the prometastatic activity of ADAMTS-1 requires its metalloproteinase activity." (PMID 22675530, 2012).
lung adenocarcinoma (4 papers, 2017 to 2024). A carcinoma that arises from the lung and is characterized by the presence of malignant glandular epithelial cells. "Moreover, bioinformatics analyses suggest that both A2M and ADAMTS1 expressions are correlated with more aggressive phenotypes of lung adenocarcinoma." (PMID 38612805, 2024).
Marfan syndrome (4 papers, 2021 to 2025). A disorder of the connective tissue. "This mouse model revealed the critical role of NO and ADAMTS1 in syndromic forms of TAAD such as Marfan syndrome." (PMID 35053160, 2021).
metastatic disease (4 papers, 2012 to 2024). "Although diminished ADAMTS1 expression frequently occurs within many primary cancers, progression toward metastatic disease is often associated with increased ADAMTS1." (PMID 38263290, 2024). "ADAMTS-1 expression was typically decreased in PrCa samples, patients with metastatic disease, and a PrCa cell line variant with higher metastatic potential but elevated in slower-growing PrCa tumors in mice." (PMID 33808504, 2021). "They found that ADAM8 was expressed significantly higher in metastatic tumors as well as identifying several proteinases of the ADAM-family (ADAM9, ADAM17, ADAM28, ADAMTS1, ADAMTS8 and ADAMTS15) -including ADAM8- which are HNSCC associated." (PMID 22369429, 2012).
non-small cell lung carcinoma (4 papers, 2006 to 2023). A group of at least three distinct histological types of lung cancer, including non-small cell squamous cell carcinoma, adenocarcinoma, and large cell carcinoma. "Taken together, these results providing evidence for an overexpression of ADAM-12 and a lower expression of ADAMTS-1 in non-small-cell lung cancer suggest that these proteases play different functions in cancer progression." (PMID 16495931, 2006). "Therefore, the methylation state of ADAMTS1 has been proposed as a potential early biomarker for colon, prostate and non-small cell lung cancer." (PMID 30004416, 2018). "However, 30% of non-small cell lung carcinoma (NSCLC) cell lines showed a down-regulation of ADAMTS1." (PMID 24213506, 2012).
osteoarthritis (4 papers, 2005 to 2024). A noninflammatory degenerative joint disease occurring chiefly in older persons, characterized by degeneration of the articular cartilage, hypertrophy of bone at the margins and changes in the synovial membrane. "To test a combined role for ADAMTS1 and ADAMTS5, we undertook pharmacological ADAMTS5 inactivation in Adamts1 null embryos using a function-blocking antibody which was originally generated to target ADAMTS5 in osteoarthritis." (PMID 38750698, 2024).
pulmonary arterial hypertension (4 papers, 2015 to 2025). Pulmonary arterial hypertension (PAH) is a group of diseases characterized by mean pulmonary artery pressure >20 mmHg and elevated pulmonary arterial resistance leading to right heart failure. "Although evidence directly linking ADAMTS1 to pulmonary arterial hypertension (PAH) continues to accumulate, its known functions in extracellular matrix (ECM) remodeling and inflammatory regulation make it a highly plausible participant in PAH pathogenesis." (PMID 41440846, 2025). "Our previous study showed that baicalin can up-regulate ADAMTS-1 expression in chronic hypoxia to inhibit collagen Ι synthesis, thereby contributing to the attenuation of pulmonary hypertension and pulmonary vessel remodeling." (PMID 28774332, 2017). "In this study, we aimed to investigate the effects of baicalin on the synthesis of collagen I in rats with pulmonary hypertension induced by hypoxia and the changes in ADAMTS-1 expression." (PMID 25716558, 2015).
acute aortic dissection (3 papers, 2023 to 2025). "In animal models of systemic ADAMTS1 knockout and ADAMTS1 haploinsufficiency, the former reduces the rupture rate of the thoracic aorta and dissection, whereas the latter is associated with a higher incidence of AA or fatal aortic dissection." (PMID 40643529, 2025). "For instance, in aortic dissection, ADAMTS1 secreted by infiltrating macrophages and neutrophils correlates with versican degradation and disease progression." (PMID 41440846, 2025). "Moreover, ADAMTS1 has been found to be overexpressed in the intima of atherosclerotic plaques, as well as in the neutrophils and macrophages accumulated in the aortic tissues of patients with acute aortic dissection." (PMID 36835545, 2023).
Alzheimer disease (3 papers, 2005 to 2024). A progressive, neurodegenerative disease characterized by loss of function and death of nerve cells in several areas of the brain leading to loss of cognitive function such as memory and language. "It is important to determine whether lactobacillus inhibits senescence by decreasing DNMT1, m1A, m6A, TDP-43, GADD45, MMP-13, and ADAMTS1, and increasing TET2, 3MST, H2S and TIMPs in RED and Alzheimer’s disease." (PMID 39456478, 2024).